FGF9 (fibroblast growth factor 9)
Diseases named in the same sentence as FGF9 in open-access papers (continued):
Sharing a sentence is not in itself a finding about the gene and the disease.
bladder cancer (4 papers, 2020 to 2023). "According to online data, the expression of lncRNA LINC01140 was obviously increased in MIBC and had a positive correlation with the expression of FGF9, suggesting an underlying effect on bladder carcinoma." (PMID 33234721, 2020). "Fibroblast cytokine 9 (FGF9) is overexpressed in many cancer cells, and its targeted receptor FGFR3c is an important driver of bladder cancer progression." (PMID 35991612, 2022). "More importantly, FGF9 was found to be a potential driver of drug resistance in gastric and bladder cancer cells, in which the presence of P4 can increase the sensitivity of chemical drugs." (PMID 35991612, 2022). "Next, we continued to investigate the dynamic effects of LINC01140 and miR-140-5p on FGF9 protein levels and bladder cancer cells." (PMID 33234721, 2020). "In conclusion, LINC01140, miR-140-5p, and FGF9 form a lncRNA-miRNA-mRNA axis that modulates the bladder cancer phenotype, affects macrophage M2 polarization through the tumor microenvironment, and in turn affects bladder cancer cell aggressiveness." (PMID 33234721, 2020). "To validate the effects of FGF9 on macrophage M2 polarization in bladder cancer, we isolated monocytes from peripheral blood (PBMCs) and stimulated the monocytes with 50 ng/ml M-CSF for polarization induction." (PMID 33234721, 2020). "FGF9 was knocked down and the specific effects of FGF9 knockdown on bladder cancer cell aggressiveness and the M2 polarization of macrophages cultured in FGF9 knockdown cancer cell culture medium were determined." (PMID 33234721, 2020). "As expected, FGF9 knockdown in T24 bladder carcinoma cells remarkably suppressed the viability, migratory capacity and invasive capacity of cells." (PMID 33234721, 2020). "To validate the hypothesis, we transfected si-FGF9 into T24 cells to generate FGF9 knockdown T24 bladder cancer cells, and performed real-time PCR and immunoblotting to verify the transfection efficiency." (PMID 33234721, 2020). "Reportedly, FGF9 can enhance M2 macrophage polarization in the infarcted diabetic heart; thus, it is reasonable to speculate that FGF9 might modulate macrophage M2 polarization, therefore affecting bladder cancer cell aggressiveness." (PMID 33234721, 2020). "Thus, LINC01140 might relieve miR-140-5p-induced inhibition of FGF9 by acting as a ceRNA, therefore affecting macrophage M2 polarization in bladder cancer." (PMID 33234721, 2020). "Thus, we speculate that FGF9 might promote bladder cancer development, possibly by promoting macrophage M2 polarization." (PMID 33234721, 2020). "More importantly, after incubation with conditioned medium derived from FGF9 knockdown T24 cells (si-FGF9-CM), the M2 polarization of macrophages was blocked, suggesting that abnormal FGF9 upregulation in bladder cancer might promote macrophage M2 polarization to accelerate cancer development." (PMID 33234721, 2020). "Similarly, culture with si-LINC01140-CM inhibited macrophage M2 polarization, indicating that LINC01140 might cooperate with FGF9 to modulate macrophage M2 polarization in bladder cancer, therefore affecting cancer cell aggressiveness." (PMID 33234721, 2020). "Thus, knocking down FGF9 significantly inhibits the aggressiveness of bladder carcinoma cells." (PMID 33234721, 2020). "Fibroblast growth factor 9 (FGF9) has been reported to enhance M2 macrophage polarization in the infarcted diabetic heart while M2 macrophages are the main type of bladder cancer-related macrophages and can accelerate bladder cancer progression." (PMID 33234721, 2020). "Since LINC01140 and FGF9 expression was positively correlated in bladder cancer tissues, the present study further searched for miRNAs that might simultaneously target both LINC01140 and FGF9." (PMID 33234721, 2020).
bladder cancer (continued). "In bladder cancer, online data analysis indicated that the expression of FGF9 was markedly increased in MIBC tissues compared within NMIBC tissues, suggesting that FGF9 upregulation might be related to the aggressiveness of bladder carcinoma cells." (PMID 33234721, 2020). "Next, differentially expressed lncRNAs related to FGF9 were analyzed, and LINC01140 was selected; the roles of LINC01140 in the aggressiveness of bladder cancer cells and the M2 polarization of macrophages cultured in cancer cell culture medium were determined." (PMID 33234721, 2020). "Notably, GSE77952 analysis identified FGF9 as a significantly upregulated gene in MIBC, in comparison with NMIBC; thus, investigating the effect of FGF9 on macrophage M2 polarization in bladder cancer and the potential mechanism could be suggested as a new strategy to treat MIBC." (PMID 33234721, 2020).
Diabetes (4 papers, 2015 to 2025). "The results suggest that LOX, HIF1α, THBS1, TGFβ2, and ITGβ1 may be involved in the diabetes‐induced downregulation of FGF9, thus promoting the development of renal EMT." (PMID 40977522, 2025). "To further research the mechanism between FGF9 and the development of DN, we examined the expression levels of FGF9 and FGFRs in a diabetes mouse model (DM group) induced by STZ injection." (PMID 40977522, 2025).
liver cancer (4 papers, 2016 to 2023). An epithelial or non-epithelial malignant neoplasm that arises from the liver. "Then, we further evaluated the change in β‐catenin stability in response to knockdown of endogenous FGF9 in liver cancer cells." (PMID 37566761, 2023). "In addition, time‐course treatment of Huh7 and HepG2 cells with cycloheximide (CHX) showed degradation of β‐catenin with prolonged treatment time, and this degradation was attenuated after FGF9 overexpression in liver cancer cells." (PMID 37566761, 2023). "Thus, the subcutaneous xenograft assay results further confirmed that FGF9 is required for fibrosis and liver cancer cells growth in vivo." (PMID 37566761, 2023). "In this study, Se-Y significantly downregulated the expression of BMP2, FGF9, and HEY1 in the liver, indicating that it can prevent liver cancer in laying hens." (PMID 37570275, 2023). "Our findings indicate that FGF9 promotes hepatic ECM accumulation and that increased expression of FGF9 worsens the pathophysiology of NASH and promotes the occurrence of liver cancer." (PMID 37566761, 2023). "In patients with liver cancer, FGFs (FGF2, FGF4, FGF5, FGF9, and FGF22) are overexpressed." (PMID 31031647, 2019).
lung adenocarcinoma (4 papers, 2016 to 2022). A carcinoma that arises from the lung and is characterized by the presence of malignant glandular epithelial cells. "Here, we show that D11 effectively inhibits signaling through FGFR3 in vitro, inhibits the growth of FGFR3-dependent FGF9-induced lung adenocarcinoma in mice, and reduces tumor-associated morbidity." (PMID 27056048, 2016). "FGF9 activates FGFR3 in the respiratory epithelium both during organogenesis and development of lung adenocarcinoma, whereas FGF7 and FGF10 signal through FGFR2b in the airway epithelium." (PMID 35675358, 2022).
lung squamous cell carcinoma (4 papers, 2017 to 2025). "However, FGF9 has also been shown to suppress renal tumor and lung squamous cell carcinoma metastases." (PMID 32366371, 2020). "Studies confirmed that mir-372-3p (38th in the prediction list) was obviously overexpressed in lung squamous cell carcinoma cells and limited the expression of FGF9 by binding to it, which contributed to the proliferation of lung squamous cell carcinoma cells (LSCC)." (PMID 30186308, 2018). "In this study, we explored the influence of miR‐372‐3p on lung squamous cell carcinoma (LSCC), and to explain the mechanism behind the effects, the targeting relationship between miR‐372‐3p and gene FGF9 was also revealed." (PMID 28440022, 2017). "The aim of this study was to study the role of miR‐372‐3p in lung squamous cell carcinoma (LSCC) cell proliferation and invasion by suppressing FGF9." (PMID 28440022, 2017). "A recent study has, for the first time, demonstrated the high expression of miR-155-5p and the low expression of Fibroblast Growth Factor 9(FGF9) in lung squamous cell carcinoma tissues and cells, revealing a negative correlation between the two." (PMID 39963112, 2025).
multiple synostoses syndrome (4 papers, 2021 to 2025). "Here, we describe the seventh family with FGF9-associated multiple synostoses syndrome." (PMID 36980996, 2023). "Pathogenic variants in NOG, GDF5, FGF9 and GDF6 have been associated, respectively, with the four molecular subtypes of multiple synostoses syndromes (SYNS1-4)." (PMID 36980996, 2023). "Thus, proximal interphalangeal fusion is typically observed in multiple synostoses syndrome linked to NOG, GDF5 and FGF9 genes, while fusion of carpal and tarsal bones is observed in patients carrying a GDF6 variant." (PMID 40673520, 2025).
Stroke (4 papers, 2012 to 2025). Sudden impairment of blood flow to a part of the brain due to occlusion or rupture of an artery to the brain. "In this respect the young rats had more genes encoding neuroprotective factors (Fgf9, Nr4a1, Tpm3) that had recovered by day14 post-stroke suggesting a better control of adult brain plasticity in young animals." (PMID 23251410, 2012). "LRRK2, CALM1, CXCR4, TLR4, CTNNB1, and CXCR2 may be implicated in AF and the hub-genes of CD19, FGF9, SOX9, GNGT1, and NOG may be associated with stroke." (PMID 30760287, 2019).
endometriosis (3 papers, 2019 to 2024). The growth of functional endometrial tissue in anatomic sites outside the uterine body. "Overexpression of FGF9 will stimulate endometriosis cell proliferation by autocrine and paracrine regulation." (PMID 34194730, 2021).
head and neck squamous cell carcinoma (3 papers, 2023 to 2025). A squamous cell carcinoma that arises from any of the following anatomic sites: lip and oral cavity, nasal cavity, paranasal sinuses, pharynx, larynx, and salivary glands. "Targeting six immune-related genes (CXCL5, ADM, FGF9, AIMP1, STC1, and CDKN2A) in individuals diagnosed with head and neck squamous cell carcinoma has shown promising results in immunotherapy triggered by periodontal disease." (PMID 37675228, 2023). "In addition, miR-372 plays an oncogenic function by down-regulating fibroblast growth factor 9 (FGF9) and p62, respectively, in both lung squamous and head and neck squamous cell carcinoma." (PMID 37445863, 2023).
ischemic stroke (3 papers, 2020 to 2024). A stroke disorder caused by obstruction of blood flow to the brain, due to thrombotic (local blood clot formation) or embolic (due to a blood clot or other material traveling from another site) event. "In addition, the expression of FGF9 was significantly and negatively correlated with the level of neutrophils by Pearson correlation coefficients, which suggested an essential effect of FGF9 in ischemic stroke." (PMID 35785353, 2022). "Therefore, therapeutic electrical stimulation improved neuronal survival in ischemic stroke by triggering NTFs such as BDNF and FGF9." (PMID 39062789, 2024). "We hypothesized that circ_0127785/ circ_0075008/miR-767-5p/FGF9 is involved in the process of ischemic stroke and brings novel insight into the diagnosis and treatment of IS." (PMID 35785353, 2022).
liver fibrosis (3 papers, 2015 to 2023). "Cytokines and chemokines upregulated by FGF9 treatment are known to play important roles in activation of neutrophils, macrophages, regulatory T cells, and endothelial cells, contributing to liver fibrosis and tumor development." (PMID 31862949, 2019). "Upregulation of Fgf9 was also observed in the livers from wild-type mice fed WD for 32 weeks, at which they develop liver fibrosis." (PMID 31862949, 2019). "Herein, we confirmed that the FGF9 controlled hepatic ECM accumulation in the NASH‐driven HCC model and established that FGF9 stimulates liver fibrosis and promotes the occurrence of HCC via ECM synthesis." (PMID 37566761, 2023). "Therefore, our study suggests that FGF9 promotes the accumulation of ECM and that liver fibrosis, rather than the proliferation ability, is the key reason for the occurrence of NASH‐driven HCC." (PMID 37566761, 2023). "In addition, it is interesting to verify the clinical implication of our findings; whether FGF9 is upregulated in human NASH, but not in liver fibrosis due to other etiologies." (PMID 31862949, 2019).
osteoarthritis (3 papers, 2021 to 2026). A noninflammatory degenerative joint disease occurring chiefly in older persons, characterized by degeneration of the articular cartilage, hypertrophy of bone at the margins and changes in the synovial membrane. "FGF9 may be involved in the occurrence and development of osteochondral diseases, and may become a new target for the treatment of osteoarthritis and other cartilage-related diseases." (PMID 33529250, 2021). "Intra-articular injection of exogenous FGF9 can delay the degradation of articular cartilage and aggravate osteophyte formation in post-traumatic osteoarthritis, but its mechanism is not clear." (PMID 33529250, 2021).
renal fibrosis (3 papers, 2024 to 2025). A final common manifestation of a wide variety of chronic kidney diseases characterized by glomerulosclerosis and tubulointerstitial fibrosis. "The increased expression levels of renal fibrosis-related genes (Grem2, Id3, Fst, Dcn) and renal damage-related genes (Runx1, Vtn, Clo6a2, Tnxb, Itga8, Timp2, Fgfr2, Fgf9) further supported the idea that miPEP31 deficiency exacerbated Ang II-induced kidney inflammation." (PMID 38992718, 2024). "These cells can produce and release FGF9 in different tissues and organs, and we speculate that the reduced secretion of FGF9 from kidney cells and the reduced release into the circulation in the presence of high glucose may be roughly responsible for further renal fibrosis." (PMID 40977522, 2025).
achondroplasia (2 papers, 2022 to 2023). Achondroplasia is the most common form of chondrodysplasia, characterized by rhizomelia, exaggerated lumbar lordosis, brachydactyly, and macrocephaly with frontal bossing and midface hypoplasia. "Transgenic mice overexpressing Fgf9 show short limbs due to reduced chondrocyte proliferation similar to bone phenotypes caused by activated FGFR3 as seen in achondroplasia." (PMID 37796615, 2023). "Targeted overexpression of Fgf9 in cartilage causes achondroplasia-like phenotypes in mice, characterized by premature closure of the growth plate, associated with significant reduction in the anteroposterior dimension of the skull." (PMID 35887171, 2022). "Importantly, FGF9 has high affinity for its receptor, FGFR3, and, as discussed later in this review, over-activating mutations in FGFR3 in humans and mice cause achondroplasia and midfacial hypoplasia." (PMID 35887171, 2022).
adenoma (2 papers, 2015 to 2017). A neoplasm arising from the epithelium. "In lung preneoplasias and adenomas of tobacco carcinogen exposed mice, the anti-estrogen fulvestrant and/or the aromatase inhibitor anastrozole blocked FGF2 and FGF9 secretion, and reduced expression of the stem cell markers SOX2 and nanog." (PMID 28445992, 2017). "After treatment with fulvestrant, anastrozole, or the combination, both preneoplasias and adenomas showed reduced staining for FGF2, FGF9, and Nanog." (PMID 28445992, 2017). "For FGF9, the combination of anastrozole and fulvestrant showed a significant reduction of high scores in preneoplasias (P < 0.0002) and in adenomas (P < 0.0002), while single treatments were not significantly different from placebo." (PMID 28445992, 2017). "Moreover, expression of key regulators of embryonic lung morphogenesis, Fgf9 and Fgf10, has been shown to trigger ADC and adenoma progression, respectively." (PMID 25713296, 2015).
brain cancer (2 papers, 2005 to 2015). A primary or metastatic malignant neoplasm affecting the brain. "Thus, we speculate whether FGF9 regulation could be modified due to CAML genotypes in FUBP3 and importantly in brain cancer pathogenesis." (PMID 26246470, 2015).
brain tumour (2 papers, 2007 to 2023). "Several negatively correlated genes, including FGF9, ARMCX1, PMP22, and ZBTB18 are involved in nervous system functions, such as glial cell growth, axon regeneration, myelin development and brain tumour suppression." (PMID 37077524, 2023).
gastric adenocarcinoma (2 papers, 2016 to 2019). "Next, the relationship between different modes of FGF9 expression and clinicopathological parameters of gastric adenocarcinomas was analyzed." (PMID 30646925, 2019).
glioblastoma (2 papers, 2015 to 2023). The most malignant astrocytic tumor (WHO grade IV). "Insufficient miR-328 in glioblastomas could lead to increased FGF9 expression and thus provide a mechanism to promote disease progression." (PMID 25978641, 2015).
Hepatic steatosis (2 papers, 2022 to 2023). Steatosis is a term used to denote lipid accumulation within hepatocytes. "In contrast, adenoviruses expressing FGF9 (Ad-FGF9) mediated FGF9 overexpression in the liver of DIO mice alleviated hepatic steatosis and improved the insulin sensitivity and glucose intolerance." (PMID 35517790, 2022). "Consistently, FGF9 knockdown in the liver of HFD-induced obese mice aggravated the symptoms of hepatic steatosis." (PMID 35517790, 2022).
Huntington disease (2 papers, 2024 to 2025). Huntington disease (HD) is a rare neurodegenerative disorder of the central nervous system characterized by unwanted choreatic movements, behavioral and psychiatric disturbances and dementia. "Other studies had shown that FGF9 promotes neurite growth in Huntington’s disease models through the ERK signaling pathway." (PMID 40526701, 2025).
influenza (2 papers, 2022 to 2025). An acute viral infection of the respiratory tract, occurring in isolated cases, in epidemics, or in pandemics; it is caused by serologically different strains of viruses (influenzaviruses) designated A, B, and C, has a 3-day incubation period, and usually lasts for 3 to 10 days. "While all PBS-treated mice recovered from WSN infection, nearly all rFGF9-treated mice succumbed to the infection, confirming that increased FGF9 in the respiratory tract enhanced influenza severity." (PMID 35675358, 2022).
meningioma (2 papers, 2012 to 2018). A generally slow growing tumor attached to the dura mater. "FGF9 underexpression was associated with aggressive meningiomas and gene overexpression with WHO grades I and II meningiomas, especially the fibroblastic morphological subtype." (PMID 29662628, 2018). "From the other 18-GEP genes, FGF9 has been consistently shown to be secreted and immunoexpressed in meningioma tissues." (PMID 29662628, 2018). "We found that several growth factors including EGFL6, IGF1, FGF2, FGF7, FGF9, and FGF11 were overexpressed in fibroblastic meningioma, especially EGFL6 gene with extremely high expression in benign meningioma tissues." (PMID 23285163, 2012). "Expression of FGF2, FGF7, FGF9, and FGF11 was significantly increased 3.19-, 48.32-, 27.15-, and 3.34-fold respectively in fibroblastic meningiomas compared with arachnoidal tissue by qRT-PCR." (PMID 23285163, 2012).
mood disorder (2 papers, 2020 to 2022). A cognitive disorder a disturbance in which the person's mood is hypothesized to be the main underlying feature. "More recent in vitro and in vivo studies suggested that FGF9 was involved in the neurodevelopment and mood disorder." (PMID 35546939, 2022). "Beside the potential role of FGF9 in neurodevelopment, FGF9 has been proposed as a novel modulator for mood disorder." (PMID 35546939, 2022). "The effect of FGF9 was found to be opposite that of FGF2, which may be due to the inverse relationship between FGF9 expression and FGF2 expression, and FGF2 and FGF9 may act as physiological antagonists to mediate emotionality and vulnerability in mood disorders." (PMID 32184729, 2020). "Here we hypothesize that the lack of FGF9 in SCZ contributes to the disease onset, and this is supported by the increasing evidence showing the crucial roles of FGF system in neurodevelopment and mood disorders." (PMID 35546939, 2022).